CD44 (CD44 molecule (IN blood group))
Diseases named in the same sentence as CD44 in open-access papers (continued):
Sharing a sentence is not in itself a finding about the gene and the disease.
tumor (continued). "Thus, it appears that HA, CD44, and MMPS are all involved in the initiation of tumor invasion and are attractive targets for tumor therapy." (PMID 21749678, 2011). "Odoux and colleagues identified CD133+ and CD44+/CD166+/EpCAMHigh cells in samples of metastatic CRC which maintained their CSC marker and histologic phenotypes in a limiting-dilution in vitro culture system as well as in ex vivo xenograft tumor models." (PMID 21318087, 2011). "Based on our results, using B6TC model to target CD44+/CD24−/ALDH+ cells for drug discovery offers a highly promising and reproducible means to identify therapies that prevent self-renewal of cancer stem cells in a tumor microenvironment." (PMID 21673810, 2011). "The pCR group also showed a tendency to have a higher proportion of CD44+/CD24− tumour cells than the non-pCR group not showing pCR in total patients (P=0.262) and in the subgroup receiving AC regimen (P=0.130)." (PMID 21559013, 2011). "The CD44+/CD24− and ALDH1+ tumour cells in post-chemotherapy specimens may constitute more specific chemoresistant CSC populations than those in pre-chemotherapy specimens, and thus may have greater clinical significance." (PMID 21559013, 2011). "As a cell adhesion molecule, CD44, a widely expressed cell-surface glycoprotein and a cell-surface receptor for hyaluronate and osteopontin, is known to mediate cellular adhesion to the ECM, which is a prerequisite for tumor cell migration." (PMID 21819617, 2011). "Consistent with the idea that Taxol may directly target CD44+ PCa cells, the intravenously injected paclitaxel greatly inhibited PC3 tumor growth as well as metastasis to the lung, pancreas and many other organs (not shown)." (PMID 21935404, 2011). "ALDHhigh/CD44+/CD24+ or ALDHlow/CD44+/CD24+ phenotypes do not appear to significantly contribute to tumor formation at low numbers of inoculated tumor cells." (PMID 21695188, 2011). "And even if patients’ survival was analysed only in the non-pCR group, we can find the tendency to have worse survival in cases with increased CD44+/CD24− or ALDH1+ tumour cell populations (P=0.127, 0.087, respectively; data not shown)." (PMID 21559013, 2011). "For H1299, HKULC4, H1650 and HCC827, as few as 10,000 CD44+ cells were able to initiate tumors in 30–68 days, but no tumor was formed from the same number of unsorted or CD44− cells after 90 days." (PMID 21124918, 2010). "Recent studies have demonstrated that induction of EMT using Twist and Snail in transformed mammary epithelial cells creates populations that are highly enriched for cancer stem cells as evidenced by increased CD44+/CD24- expression, mammosphere formation and tumor seeding ability." (PMID 20615238, 2010). "In tumors showing extensive CD44 expression, it is possible that not all tumor cells are responsible for tumor initiation." (PMID 21124918, 2010). "For HKULC2 and H23, although SB formation was observed, no xenograft tumor was formed using 200,000 unsorted, CD44+ or CD44− cells." (PMID 21124918, 2010). "Finally, CD44, CD166, CD29, CEACAM5, cadherin 17, and biglycan were identified by mass spectrometry to be enriched in CD133+ tumour spheroid cells." (PMID 20332776, 2010). "Loss of membranous E-cadherin, CD44, CD44v6, EpCAM and CD166 expression have all been reported and often are not expressed within tumor budding cells themselves." (PMID 21317460, 2010). "In this study, we found an overexpression of uPA, CD44 and MDR1 and a colocalisation of uPA and CD44, uPA and MDR1, CD44 and MDR1 in cancer cells and stromal cells from most primary tumours and matched metastatic lesions, and further confirm the finding in EOC cell lines." (PMID 19603017, 2009). "Moreover, if the candidate CD44 and ALDH-labels were valid surrogate markers for CSC, then CSC seemed to reside in discrete protected microdomains (niches) in the MPE-tumor clusters." (PMID 19536353, 2009).
tumor (continued). "Moreover, CD44 appearance was detectable in 94% of 176d HBCEC and in 99% of 462d HBCEC, suggesting little if any changes of both, CD24 and CD44 during long term tumor culture." (PMID 19751512, 2009). "In high-grade EOC (Grade 2 and 3), the most tumour stroma also showed a strong positive reaction for uPA, CD44 and MDR1 in primary tumours and metastatic lesions (data not shown)." (PMID 19603017, 2009). "In concordance with the higher number of CD44+CD24− cells in the DU145 cell line, NOD/SCID mice injected with 3 million DU145 cells formed tumours earlier (approximately 9 days) that were 14 times larger at 39 days than NOD/SCID mice injected with LNCaP cells (266.5 vs 18.2 mm3, respectively)." (PMID 18268494, 2008). "The majority of tumors included at least a few double-negative (CD44-/CD24-) tumor cells, while a complete lack of both proteins was evident in 35% (83/240)." (PMID 18559090, 2008). "Furthermore, injection of as few as 100 CD44+CD24− cells resulted in a single tumour (1/5), whereas 100 CD44+CD24−-depleted cells or 100 total LNCaP cells were unable to form a tumour (0/5)." (PMID 18268494, 2008). "The presence of CD44-/CD24+ tumor cells was solely associated with strong HER2 staining (P = 0.002) and not with any other tumor characteristics." (PMID 18559090, 2008). "Significantly, injection of 1000 CD44+CD24− cells resulted in tumours in 100% (5/5) of mice, whereas 1000 CD44+CD24−-depleted cells failed to form tumours in any mice (0/5)." (PMID 18268494, 2008). "The trend towards more frequent ESA+CD44+ cells in CPA-treated tumors generally held true independent of tumor volume and was more pronounced at higher CPA doses (e.g. 38 mg/kg versus 25 mg/kg; data not shown)." (PMID 18560594, 2008). "Finally, in cell lines that exhibit two distinct CD44/CD24 populations (for example, SUM149), all three markers are required to enrich correctly for tumor-initiating stem-like cells." (PMID 18366788, 2008). "We did not see any association between the CD44+/CD24- status and markers known to be important for the clinical outcome, including tumor size, nodal status or S-phase fraction." (PMID 18559090, 2008). "To validate that this culture system supports maintenance of TG cells, we sorted ESA+CD44+CD166+ CoCSC in limiting dilution into plates containing Mitomycin C-treated 3T3 or MEF feeder cells as support, depending on the tumor line used: UM-C4 or UM-C6, respectively." (PMID 18560594, 2008). "The inverse proportion between CD44 expression in tumour cells and the number of lymphatics expressing VEGFR-3 may be due to the role of CD44 in homophilic cell aggregation." (PMID 17222331, 2007). "Note that the advanced tumor sample in Lane 13, the most predictive for our differential splice patterns, does not display alternative splicing of CD44." (PMID 17192196, 2006). "sCD44 can disrupt CD44/MMP-9 clusters and inhibit tumor metastasis in vivo." (PMID 19570245, 2002). "The absence of TRKA expression on CD44-positive or N-MYC non-amplified tumours permits the characterization of a subgroup of patients with intermediate prognosis." (PMID 9099963, 1997). "CD74-mediated signaling is often co-activated by CD44, a major ECM receptor that also serves as a main cancer stem cell marker, leading to the activation of key oncogenic pathways, including the MAPK/ERK and PI3K/Akt pathways, which promote tumor cell proliferation, migration, and survival." (PMID 41597235, 2026). "Evaluation of cancer stem cell-associated markers showed consistent expression of CD44, Nanog, Oct3/4, and Sox2 in the original tumours and cell lines, while CD133, Nestin, and Trop2 were present in the tumours but absent in vitro, indicating selective loss of specific stem-like populations." (PMID 41828941, 2026).
tumor (continued). "Furthermore, CTLA4+ T cells secrete S100A4, which induces a stem-like phenotype in TNBC cells, while CD44 has been recognized as a stem cell marker in BC that binds multiple ECM components, notably hyaluronic acid (HA), modifying tumor behavior through co-receptor interactions." (PMID 41602418, 2026). "Additionally, a low CD3+ TIL density significantly correlated with old age (p = 0.012) and high CD44 expression in tumor cells (p = 0.030) but not with the expression of other CSC markers or clinicopathologic characteristics." (PMID 40647395, 2025). "In addition, we found that fibroblasts, as signal senders, may cooperate with TREM1+ PMN-MDSCs in extracellular matrix remodeling and tumor progression by secreting collagen and FN1 to interact with the CD44." (PMID 41413734, 2025). "Notably, its targeted impact on the CD44+/CD24–population suggests that niclosamide could enhance the sensitivityof CSCs to treatment, thereby preventing tumor recurrence." (PMID 40521512, 2025). "Indeed, depletion of various stemness markers such as cluster of differentiation 44 (CD44) in breast CSCs or octamer-binding transcription factor 4 (OCT4) and SRY-Box Transcription Factor 2 (SOX2) in colon CSCs, prevented tumor metastasis and tumor growth." (PMID 39981232, 2025). "Additionally, we conformed the outer-expressing pattern of CD44 by immunohistochemistry (IHC) staining in both mouse and human CRC tissue sections, revealing a distinct spatial expression of CD44 at the tumor edge region." (PMID 40069574, 2025). "SPP1 expression is upregulated in ICCA tumor epithelial cells, and SPP1-CD44 interactions impede T cell proliferation, but immunosuppressive T cells in the TME may escape this suppression by reducing CD44 expression." (PMID 40070825, 2025). "Additionally, given the role of stemness in tumor aggressiveness, we explored whether the stemness phenotype of the CRC cells, defined by CD44 and CD133 surface markers expression, influenced macrophage polarization." (PMID 40160820, 2025). "The tumor-suppressive outcome is driven by combined molecular changes: downregulation of SPARCL1 and PSME3, coupled with upregulation of the NF-κB inhibitor NFKBIA and downregulation of CD44 and CCL15, collectively promotes apoptosis while suppressing proliferation, migration, and angiogenesis." (PMID 41465234, 2025). "Importantly, the ratios of Treg cells to CD44+ CD8+ T cells in both the dLNs and tumor-infiltrating lymphocytes were remarkably reduced in the FX1-treated and combination treatment group, which suggested that the therapeutic effects of FX1 are largely mediated by Treg cells." (PMID 40290124, 2025). "Foundational xenograft work identified a CD44+/CD24+/ESA+ CSC subpopulation with robust tumor-initiating capacity and self-renewal; as few as ~100 cells formed tumors and showed elevated Sonic Hedgehog expression, establishing CSC linkage to developmental signaling and tumor initiation in vivo." (PMID 40868290, 2025). "We enriched the CSC population through sphere culture from A549 and H1299 tumor-bearing mice and verified the enrichment using western blotting and flow cytometry to detect stem cell transcription factors (NANOG, OCT4, SOX2) and CSC surface markers (CD44, CD133)." (PMID 40093893, 2025). "Additionally, CRYAB and CD44 are highly co-expressed in aggressive GBM, synergistically regulating cytoskeletal remodeling and anti-apoptotic signaling pathways, which significantly enhances the tumor's recurrence after surgery." (PMID 41201287, 2025). "A decrease in CD44 may thus indicate depletion, phenotypic shifts, or reprogramming of CD44-expressing non-tumor cells in the metastatic niche, rather than changes in tumor cells per se." (PMID 40805225, 2025). "Additionally, the expression of the CSC markers CD133 and CD44 was significantly upregulated in CRPC tumors, further supporting the hypothesis that CAFs promote tumor progression by regulating PCSC properties." (PMID 40735647, 2025).
tumor (continued). "In contrast, the tumor core region is enriched with genes related to cell proliferation (such as MKI67), while cells in the invasive margin express high levels of migration-related molecules (such as CD44 and the MMP family) and stress response genes (such as HSPB1/CRYAB)." (PMID 41201287, 2025). "When FL/GM-DCs loaded with B16-OVA tumor lysates were co-cultured with CD4+T cells that had been isolated from OT-II mice, we detected a significant increase in the activation and proliferation of CD44+CD4+T cells relative to those co-cultured with GM/IL4-DCs (37% vs. 25.5%)." (PMID 40977690, 2025). "Loss of FAT1 function activates the Ca2+/calmodulin-dependent protein kinase II (CAMK2)–CD44–SRC axis, promoting YAP1 nuclear translocation and zinc finger E-box binding homeobox 1 (ZEB1) expression, thereby stimulating the mesenchymal state and increasing tumor stemness and metastasis." (PMID 41368628, 2025). "Moreover, the CXCL12γ isoform has been shown to accelerate tumor progression in CRPC by promoting the PCSC phenotype via CXCR4-mediated PKCα/NF-κB activation, resulting in an increase in the population of CD133+CD44+ CSC-like cells in CXCL12γ-overexpressing tumors." (PMID 40735647, 2025). "Although the current study examined the effects of HA and CD44 on the β-catenin–GFAT axis only in HeLa and PANC-1 cells, which limits its diversity, other independent studies also support a functional connection among hyaluronan synthesis, GFAT, and β-catenin signaling across various tumor types." (PMID 41461315, 2025). "Moreover, the frequencies of CD8+ and CD4 + T cells, and the relative abundance of naïve T cells (CD44-CD52L+), effector/memory T cells (CD44+CD62L−), and central memory T cells (CD44+CD62L+) cells was unaffected in the tumor-draining lymph nodes." (PMID 40796746, 2025). "CD44, through alternative splicing and interaction with the tumor microenvironment, is not merely a marker of cancer-initiating cells but also actively contributes to tumor progression by facilitating cell migration, niche preparation, epithelial-mesenchymal transition, and resistance to apoptosis." (PMID 40805206, 2025). "After sorting CD44-high and CD44-low populations from 7 days KPY organoids, we transplanted the same number of cells from each population by intratracheal instillation as described, and the mice were euthanized two months after transplantation to quantify the tumor burden." (PMID 39930268, 2025). "This may be explained by the fact that Gal-9 released from tumor cells suppresses anti-tumor immunity by interacting with various surface receptors including TIM-3, PD-1, VISTA, CD40, CD44 and DR3 in T lymphocytes, leading to T cell exhaustions and immune tolerance." (PMID 40138336, 2025). "Our findings indicate that the APP and collagen signaling pathways mediated by PRELP+ CAFs may inhibit immune cell function, promote immune evasion by tumor cells, remodel the ECM, and influence immune cell infiltration and activity through the APP-CD74 and collagen-CD44 axes." (PMID 41031085, 2025). "Moreover, CD90, CD49, CD44, CD24, and ALDH, in addition to EpCAM, are a few surface markers reported for the isolation of BCSCs, as they tend to have altered expression levels when compared to those of other bulk tumor cells." (PMID 38920716, 2024). "Moreover, bystander CD8+ T-cells without tumor antigen specificity, i.e., CD44+CD8+ T-cells, contributed to the elimination of tumor cells." (PMID 39105814, 2024). "The absence of CD44 has a notable impact on MMP9 levels within the tumor microenvironment." (PMID 38473812, 2024). "Hence, CP1-LVs with an appropriate amino/hydroxyl ratio selectively adsorbed proteins with low pI, including CD44 and OPN, resulting in the adsorption of many tumor TIF proteins, which may obviously affect the subsequent interaction with tumor cells." (PMID 38326312, 2024).
tumor (continued). "As expected, the vast majority of SIINFEKL+ CD8+ T cells in the tumor expressed CD69 and lacked CD62L, with a fraction of CD69+ cells co‐expressing CD103, a marker associated with tissue residency that is lacking on circulating CD44+ T cells." (PMID 39584189, 2024). "Similarly, the majority of NSGCTs (24 out of 38) found negative for CD44 staining in tumor cells (≤10% tumor cell positivity), whereas 14 out of 38 NSGCTs were positive for CD44 expression (>10% tumor cell positivity)." (PMID 38796656, 2024). "Hence, we aimed to evaluate if quantifiable parameters could be established for the expression of CD44, EGFR, vimentin, and E-cadherin in terms of predicting tumor aggressiveness and prognostic significance, if any, in OSCC." (PMID 39050298, 2024). "Finally, Dac treatment suppressed the tumor growth and restored the activation of CD44+CD8+ T cells in control MC38 tumors but not in ATP6V0A1-suppressing MC38 tumors." (PMID 38971819, 2024). "Considering our previous analysis of tumor slices and the present work, CD44 may serve as a general GBM marker rather than a SLGC marker." (PMID 38306361, 2024). "To better distinguish the phenotypes of tumor antigen-specific CD8 T cells that track to the TdLN, and the effect of radiation on these populations, we identified the distribution of these cells into CD44+CD62L− effector and CD44+CD62L+ memory populations in the TdLN." (PMID 38789721, 2024). "On the one hand, although CD44-ICD itself lacks kinase activity, it can interact with cofactors and adaptor molecules to regulate actin-cytoskeleton network remodeling and various cellular signaling pathways, which subsequently enhance the invasive behavior of tumor cells." (PMID 39145451, 2024). "Gene expression profiling of CD44+/α2β1hi/CD133+ primary cancer cells reveals a significant over-representation of the JAK-STAT signaling pathway, indicating aberrant alterations of this pathway in CSCs could accelerate the tumor load." (PMID 39175878, 2024). "Despite the fact that the absolute number of CD117+CD44+, CD117+EGF+ and CD117+EGF+CD44+ cells did not increase in tumor formation, the relative content of Sox2+ cells in these populations was significantly higher compared to similar indicators in intact animals." (PMID 38664641, 2024). "Taking advantage of CD44 overexpression on the surface of most tumor cells and high levels of GSH in tumor microenvironment, the nanosystem could be specifically uptake by breast cancer cells and rapidly degrade and release functional cargoes (β-lap, CaO2 and Fe2+) in response to intracellular GSH." (PMID 38166978, 2024). "According to these in-human data, tumor uptake of 18F-FSPG might be representative of redox status but not necessarily the status of CD44." (PMID 38609981, 2024). "We examined their unique cell morphology characteristics (A) and analyzed a wide range of tumor markers (B), including the PD‐1/PD‐L1 status, PD‐L2 expression, EMT markers (vimentin, E‐cadherin, and N‐cadherin), oncogenes (TWIST and Snai1), and the HNC stem cell marker CD44." (PMID 38103190, 2024). "CD44+CD62L− effector phenotype cells were rare among the unconverted CD8 T cells that did not recognize SIY in the TdLN, indicating that a large proportion of the effector populations in the TdLN either emigrated from the tumor to the TdLN or recognize the immunodominant tumor antigen SIY." (PMID 38789721, 2024). "Consistently, in vivo limiting dilution assay showed, compared with the sh‐ctrl‐ALDH+/CD44+ fraction, the sh‐ctrl‐ALDH−/CD44− fraction and shGSTP1‐ALDH+/CD44+ fractions showed significantly reduced CSC frequency, tumor incidence, and longer tumor‐free survival, respectively." (PMID 36709476, 2023). "Upregulated CD44 under such severe hypoxia may primarily activate tumor cell migration and invasion rather than tumor cell proliferation." (PMID 37835592, 2023). "Thus, our in vitro results suggest that Cd44+/+ and Cd44−/− cells do not differ in their tumor-initiating capability." (PMID 37174657, 2023).